AIMP2 (aminoacyl tRNA synthetase complex interacting multifunctional protein 2)
Description:
Required for assembly and stability of the aminoacyl-tRNA synthase complex. Mediates ubiquitination and degradation of FUBP1, a transcriptional activator of MYC, leading to MYC down-regulation which is required for aveolar type II cell differentiation. Functions as a proapoptotic factor.
Synonyms: JTV1; PRO0992; p38; JTV-1; HLD17
Tractability: Small molecule: a structure with a bound ligand is known. PROTAC: UniProt records ubiquitination sites on it; ubiquitination databases record sites on it; its protein half-life has been measured; a small molecule that binds it is known.
Gene: Protein-coding gene on chromosome 7 (6,009,255 to 6,023,834, forward strand). Ensembl gene ENSG00000106305.
Subcellular location: Cytoplasm, cytosol; Nucleus
Subcellular location (Human Protein Atlas): Cytosol
Pathways (Reactome):
Developmental Biology: Transcriptional and post-translational regulation of MITF-M expression and activity
Metabolism: Selenoamino acid metabolism
Metabolism of proteins: Cytosolic tRNA aminoacylation
Gene Ontology:
Molecular function: protein binding; protein-macromolecule adaptor activity; molecular adaptor activity
Biological process: tRNA aminoacylation for protein translation; protein-containing complex assembly
Cellular component: aminoacyl-tRNA synthetase multienzyme complex; cytosol; membrane; cytoplasm; nucleus
Genetic constraint (gnomAD): Loss-of-function variants: 21 observed, 27.32 expected, observed/expected ratio (o/e) 0.77, 90% interval 0.54 to 1.11. The upper end of that interval is the gene's LOEUF score, 1.11, which puts it in group 4 of 6, group 1 being the genes least tolerant of losing a copy. Missense variants: 515 observed, 432.65 expected, observed/expected ratio (o/e) 1.19, 90% interval 1.11 to 1.28. Synonymous variants: 210 observed, 181.05 expected, observed/expected ratio (o/e) 1.16, 90% interval 1.04 to 1.3.
Gene-disease validity (ClinGen):
ClinGen rates the evidence that AIMP2 causes each of these diseases.
leukodystrophy, hypomyelinating, 17 (autosomal recessive): Definitive.
Homologues: Orthologues: chimpanzee AIMP2 (98% identical), macaque AIMP2 (98% identical), dog AIMP2 (90% identical), guinea pig AIMP2 (90% identical), rat Aimp2 (88% identical), rabbit AIMP2 (88% identical), mouse Aimp2 (87% identical), pig AIMP2 (82% identical), tropical clawed frog aimp2 (65% identical), zebrafish aimp2 (56% identical), Drosophila melanogaster AIMP2 (26% identical).
Diseases named in the same sentence as AIMP2 in open-access papers:
AIMP2 is named in the same sentence as 48 diseases in open-access papers, as found by Europe PMC text mining. Sharing a sentence is not in itself a finding about the gene and the disease. The quoted sentences say what the papers report.
lung carcinoma (12 papers, 2017 to 2023). "AIMP2-DX2 interferes with the tumor suppressor activity of AIMP2, and is also overexpressed in lung cancer, which suggests a diagnostic role for lung cancer." (PMID 34679529, 2021). "AIMP2-DX2, an exon 2-deleted splice variant of AIMP2 (aminoacyl-tRNA synthetase-interacting multifunctional protein 2), is highly expressed in lung cancer and involved in tumor progression in vivo." (PMID 32471182, 2020). "In addition, AIMP2 and its splicing variant are involved in the development of lung cancer." (PMID 33330488, 2020). "Background and objective: Methionyl-tRNA synthetase (MARS) and A variant of Aminoacyl-tRNA synthetase interacting multifunctional protein 2 (AIMP2) with an exon 2 deletion (AIMP2-DX2) are known to be overexpressed in lung cancer." (PMID 34679529, 2021). "Of note, AIMP2 had a tumor suppressor activity on lung cancer cells by Smad ubiquitination regulatory factors 2 (Smurf2)." (PMID 34660690, 2021). "Another example of a cis-acting regulatory element related to an aberrant splicing event in lung cancer occurs in the Aminoacyl-tRNA synthetases (ARS)-interacting multifunctional protein 2 (AIMP2) gene." (PMID 34065983, 2021). "While AIMP2 is a tumor suppressor, an exon 2-depleted splice variant of AIMP2 (AIMP2-DX2, hereafter abbreviated as DX2) is highly expressed in human lung cancer." (PMID 32549310, 2020). "We can also see significant mRNA overexpression of AIMP2 in lung cancers (LUAD and LUSC) and ovarian cancer (OV)." (PMID 33266490, 2020). "In addition, the application of Q1 as a cutoff value in lung cancer may bias this result because the optimal cutoff AIMP2-DX2/AIMP2 expression ratio may differ for each cancer type." (PMID 33128014, 2020). "Notably, AIMP2-DX2, a splicing variant of AIMP2 lacking exon 2, was induced by oncogenes in human lung cancer cells and could block oncogene-induced apoptosis and senescence by inhibiting p14/ARF68." (PMID 34039958, 2021). "Through the screening of a drug repositioning library from KCB, pyrimethamine was identified as a hit chemical for the treatment of lung cancer, selectively inhibiting DX2 over AIMP2 (IC50 > 100 μM) with an IC50 value of 0.73 μM in A549 cells expressing nanoluciferase-tagged DX2." (PMID 32549310, 2020). "AIMP2-DX2, as a splice variant of AIMP2 lacking exon 2, was highly expressed in human lung cancer cells, and the ratio of AIMP2-DX2 to normal AIMP2 was increased with cancer progression." (PMID 32709848, 2020).
Parkinson disease (7 papers, 2020 to 2025). A progressive degenerative disorder of the central nervous system characterized by loss of dopamine producing neurons in the substantia nigra and the presence of Lewy bodies in the substantia nigra and locus coeruleus. "The differentially methylated bb-CpG cg11725581 in Parkinson’s Disease dataset is mapped between the AIMP2 and USP42 genes." (PMID 39060467, 2024). "As a representative therapeutic survival gene for Parkinson’s disease treatment, we integrated DX2, an antagonistic splice variant of the apoptotic gene AIMP2, known to be implicated in Parkinson's disease, into the vector." (PMID 38218903, 2024). "Parthanatos represents a critical molecular aspect of Parkinson's disease, wherein AIMP2 aberrantly activates PARP-1 through direct physical interaction." (PMID 38172953, 2024). "Preclinical brain-permeable AIMP2 inhibitors have shown some promise in Parkinson disease, which may be tested in glioma cell lines in future studies." (PMID 40874786, 2025). "However, mutant Parkin1 fails to bind AIMP2, which is one of the molecular mechanisms underlying mutant Parkin1-induced parkinsonism." (PMID 38172953, 2024). "Consequently, we examined whether DX2 competes with AIMP2 for PARP-1 activation and is therapeutically effective in Parkinson’s disease." (PMID 38172953, 2024).
breast carcinoma (5 papers, 2023 to 2025). "Furthermore, we confirmed that the expression level of AIMP2 was associated with tumor immune infiltration and the tumor microenvironment, particularly in breast cancer (BRCA)." (PMID 38235352, 2023). "In addition, pan-cancer bioinformatic analyses have identified AIMP2 as an immune-associated molecule whose aberrant expression correlates with tumour immune infiltration and patient survival, suggesting its potential as a biomarker in breast cancer immunomodulation." (PMID 41284319, 2025). "Compared with that in normal breast cells, AIMP2 expression was high in breast cancer cells, whereas QARS1 expression was low in breast cancer cells; the expression of IYD was not clear." (PMID 40493339, 2025). "To investigate the AIMP2-related co-expression network in breast cancer, we performed a WGCNA based on the BRCA dataset." (PMID 38235352, 2023). "Lastly, siRNA-mediated knockdown of AIMP2 inhibited the proliferation and migration of breast cancer cells in vitro." (PMID 38235352, 2023). "Our results demonstrated that in breast cancer, high AIMP2 expression was predominantly found in MTORC1 signaling, MYC TARGETS_V2, UNFOLDED_ PROTEIN_RESPONSE, and other signaling pathways." (PMID 38235352, 2023). "Qiu and colleagues reported in their pan-cancer study that higher AIMP2 expression may be a potential biomarker for breast cancer in the context of immunotherapy response." (PMID 40874786, 2025). "In vitro cell experiments indicated that AIMP2 expression in tumor tissues was higher than in normal tissues, and inhibiting AIMP2 expression could affect the biological behavior of breast cancer cells." (PMID 38235352, 2023). "GSEA analysis of the relationship between AIMP2 and breast cancer is presented in Fig. (7B)." (PMID 38235352, 2023). "Additionally, we investigated AIMP2's impact on breast cancer (BRCA) proliferation and migration using cell counting kit 8 (CCK-8) assay, transwell assays, and western blot analysis." (PMID 38235352, 2023). "Analysis of breast cancer gene expression data from the TCGA database revealed that the expression of AIMP2 and IYD was elevated in breast cancer tissues, whereas the expression of QARS1 was elevated in normal tissues." (PMID 40493339, 2025).
leukodystrophy (4 papers, 2020 to 2024). Leukodystrophies are a group of rare, progressive, metabolic, genetic diseases that affect the brain, spinal cord and often the peripheral nerves. "We report a case of a 7-month-old infant with a complex clinical presentation, including weight loss, severe anemia, skeletal abnormalities, microcephaly and MR imaging features of leukodystrophy with a novel mutation in AIMP2." (PMID 35140751, 2022). "In addition, variants in two non-aaRS MSC constituents, i.e., AIMP1 and AIMP2, also cause leukodystrophy, although this is likely to be secondary to a primary neurodegenerative process." (PMID 38769304, 2024).
ovarian carcinoma (4 papers, 2020 to 2025). A malignant neoplasm originating from the surface ovarian epithelium. "AIMP2-DX2 reduced the pro-apoptotic activity of TNF-α by competitively inhibiting the binding of AIMP2 to TRAF2, thereby contributing to the chemoresistance of ovarian cancer." (PMID 32709848, 2020).
colorectal cancer (3 papers, 2022 to 2023). A primary or metastatic malignant neoplasm that affects the colon or rectum. "In colorectal cancer, AIMP2 participates in the regulation of adenoma initiation via Wnt/β-catenin signaling." (PMID 37524692, 2023). "Deregulations of pathway members including AIMP1, AIMP2 and AIMP3 were observed in gastric and colorectal cancer." (PMID 35044082, 2022).
neuroblastoma (3 papers, 2013 to 2024). Neuroblastoma (NB) is the most common solid, extracranial childhood tumor. "Consistent with the role of AIMP2 in mediating cell toxicity, we showed that coexpression of WT VPS35 but not mutant VPS35 prevented cell toxicity caused by elevated AIMP2 in SH-SY5Y neuroblastoma cell line." (PMID 28383562, 2017). "Plasmids expressing either AIMP2 or DX2 were introduced into SH-SY5Y neuroblastoma cells." (PMID 38172953, 2024). "To determine whether DX2 acts as a competitive inhibitor of AIMP2, suppressing AIMP2-induced PARP-1 activation and neuronal cell death, we transfected neuroblastoma cells with DX2-plasmid vectors and -siRNA, and subsequently measured the binding of AIMP2 to PARP-1." (PMID 38172953, 2024). "Additionally, INNO-406 treatment prevented MPP+-induced cellular toxicity in SHSY-5Y neuroblastoma cells suggesting that our in vivo observation of INNO-406 prevention of parkin phosphorylation and AIMP2 accumulation might play a major role in cell survival." (PMID 23741470, 2013).
glioma (2 papers, 2025). A benign or malignant brain and spinal cord tumor that arises from glial cells (astrocytes, oligodendrocytes, ependymal cells). "Through multiomic and single-cell analyses, AIMP2 is shown to be upregulated in aggressive gliomas and linked to angiogenesis." (PMID 40874786, 2025). "Further functional studies are needed to delineate the regulatory or structural roles of AIMP2 in glioma pathophysiology and to determine whether it has actionable potential as a therapeutic target." (PMID 40874786, 2025). "We found that AIMP2 and AIMP3 were significantly upregulated in recurrent gliomas compared with primary gliomas." (PMID 40874786, 2025). "Here, we report aberrant protein expressions of AIMP1, AIMP2, and AIMP3 in gliomas compared with normal brain and their significantly higher mRNA expression in higher-grade compared with lower-grade tumors." (PMID 40874786, 2025).
hepatocellular carcinoma (2 papers, 2020 to 2023). A malignant tumor that arises from hepatocytes. "Similar to AML, samples with an AIMP2-DX2/AIMP2 expression ratio ≥Q1 tended to exhibit an inferior OS in colon carcinoma (log-rank P = 0.28), and hepatocellular carcinoma (log-rank P = 0.24)." (PMID 33128014, 2020). "For colon adenocarcinoma and hepatocellular carcinoma in the ICGC/TCGA database, although statistical significance was not met, patients with an AIMP2-DX2/AIMP2 expression ratio ≥Q1 displayed worse survival outcomes." (PMID 33128014, 2020).
nasopharyngeal carcinoma (2 papers, 2018 to 2020). A carcinoma arising from the nasopharyngeal epithelium. "The same studies that showed how DX2 disrupts the normal function of AIMP2 also demonstrated clear overexpression of DX2 in lung, ovarian, and nasopharyngeal cancers." (PMID 33266490, 2020).
acute myeloid leukemia (1 paper, 2020). Acute myeloid leukemia (AML) is a group of neoplasms arising from precursor cells committed to the myeloid cell-line differentiation. "Here, we found that AIMP2-DX2/AIMP2 expression ratio is strongly correlated with major cancer signaling pathways and poor prognosis, particularly in acute myeloid leukemia (AML)." (PMID 33128014, 2020).
Alzheimer disease (1 paper, 2019). A progressive, neurodegenerative disease characterized by loss of function and death of nerve cells in several areas of the brain leading to loss of cognitive function such as memory and language. "Moreover, it would be interesting to evaluate whether alterations on AIMP2 and parkin mRNA levels are movement disoder specific by comparing with other neurodegenerative cognitive disorders like Alzheimer’s disease." (PMID 31366968, 2019).
Burkitt lymphoma (1 paper, 2020). A rare form of malignant mature B-cell non-Hodgkin lymphoma. "As a comparison, we used Namalwa Burkitt’s lymphoma cells, which expressed a low ratio of AIMP2-DX2/AIMP2." (PMID 33128014, 2020).
cystic fibrosis (1 paper, 2018). Autosomal recessive disorder caused by pathogenic variants in the CFTR gene (cystic fibrosis transmembrane conductance regulator), which encodes a chloride and bicarbonate channel expressed in epithelial cells, and follow the diagnosis criteria. "Cystic fibrosis transmembrane conductance regulator (CFTR)-ΔF508, α-synuclein, and aminoacyl-tRNA synthetase complex-interacting multifunctional protein-2 (AIMP2) are aggregation-prone proteins associated with the development of cystic fibrosis or PD." (PMID 30469013, 2018).
desmoid tumor (1 paper, 2018). A desmoid tumor (DT) is a benign, locally invasive soft tissue tumor associated with a high recurrence rate but with no metastatic potential. "The AIMP2 was thusly found to regulate the Wnt/beta-catenin signaling in the intestinal tract; however, it is not clear from their results if or how the signaling cascade would be altered with the known desmoid tumor mutation of beta-catenin, T41A or S45F." (PMID 29330550, 2018).
fatty liver (1 paper, 2024). "A recent study has revealed that aging-related fatty liver induced by the dysregulation of O-GlcNAcylation is closely associated with aminoacyl tRNA synthetase complex-interacting multifunctional protein 2 (AIMP2) and poly (ADP-ribose, PAR) polymerase 1 (PARP1)." (PMID 38786029, 2024). "O-GlcNAc signaling has also been found to be significantly activated in aging-related fatty liver to reduce AIMP2 degradation." (PMID 38786029, 2024).
head and neck cancer (1 paper, 2020). A primary or metastatic malignant neoplasm affecting the head and neck. "In our study, AIMP2 is amplified at the DNA level in lung and head and neck cancers (LUAD, LUSC, HNSC)." (PMID 33266490, 2020).
hypomyelinating leukodystrophy-17 (1 paper, 2020). "Other than DX2, no genetic alterations of AIMP2 is known to be associated with human cancers, although a homozygotic nonsense mutation of AIMP2 has been reported to be associated with hypomyelinating leukodystrophy-17, an autosomal recessive neurodevelopmental disorder." (PMID 32471182, 2020).
multiple system atrophy (1 paper, 2019). Multiple system atrophy (MSA) is a neurodegenerative disorder characterized by autonomic failure (cardiovascular and/or urinary), parkinsonism, cerebellar impairment and corticospinal signs with a median survival of 6-9 years. "Moreover, alteration pattern of parkin and AIMP2 in PD was distinct from another neurodegenerative disease, multiple system atrophy." (PMID 31366968, 2019).
myeloma (1 paper, 2020). "Lastly, we used KMS-12-BM myeloma cells, which expressed the intermediate AIMP2-DX2/AIMP2 expression ratio." (PMID 33128014, 2020).
Onset (1 paper, 2023). The age group in which disease manifestations appear. "AIMP2 has been identified as a candidate gene for late-onset Parkinson’s disease, expressed in the mesencephalon, and associated with dysregulation in PD associated pathways." (PMID 38025430, 2023).
α-synucleinopathy (1 paper, 2022). "AIMP2 has been shown to increase α-synuclein aggregation, and this α-synucleinopathy may partly contribute to neurite toxicity in PC12 cells." (PMID 36711211, 2022).